DYRK2 (dual specificity tyrosine phosphorylation regulated kinase 2)
Diseases named in the same sentence as DYRK2 in open-access papers (continued):
Sharing a sentence is not in itself a finding about the gene and the disease.
cancer (continued). "Finally, to investigate the relationship between active DYRK2 -using Y382 phosphorylation at the activation loop as marker- and USP28 abundance in cancer, we analyzed CPTAC phospho-proteomic and proteomic data." (PMID 40858801, 2026). "Consequently, targeting DYRK2 inhibition, as seen with the effectiveness of the inhibitor LDN192960 in myeloma cells, emerges as a promising strategy in cancer therapy." (PMID 38474160, 2024). "Although some studies have used cell lines and/or xenografts to elucidate the mechanism of DYRK2 function, these studies are not sufficient to understand the role of DYRK2 in cancers." (PMID 37886981, 2023). "To further consolidate this, we explored multiple databases to understand whether DYRK2 and HSF1 expression correlate across diverse cancer datasets." (PMID 36622366, 2023). "In addition, the overlapping expression of DYRK2 and HSF1 was observed across all cancers in TCGA database." (PMID 37886981, 2023). "Intriguingly, expressions of DYRK2 and HSF1 seemed to be either significantly coup-regulated or codown-regulated in response to standard-of-care clinical chemotherapeutic combination regimens across diverse cancers." (PMID 36622366, 2023). "Indeed, targetting DYRK2 with various small-molecule inhibitors like curcumin, harmine, or LDN192960 can result in cancer reduction both in vitro and in vivo." (PMID 36622366, 2023). "Moreover, we saw a positive correlation (Spearman coefficient R=0.33) between DYRK2 and HSF1 expression across all cancers in TCGA database." (PMID 36622366, 2023). "Although there have been studies correlating DYRK2 with a number of human cancers, there has been no pan-cancer analysis." (PMID 36104345, 2022). "As such, DYRK2 may offer value as a prognostic biomarker in this cancer type, with CRC patients exhibiting lower levels of DYRK2 expression potentially requiring closer monitoring than patients expressing higher levels of this gene." (PMID 36577753, 2022). "DYRK2 upregulation usually has a negative impact in cancer-related conditions and a positive impact in non-malignant conditions." (PMID 36161154, 2022). "But not all reports demonstrate that DYRK2 inhibits cancer initiation and growth as a cancer suppressor." (PMID 35614066, 2022). "Despite the important roles played by DYRK family members in various types of cancers with the exception of DYRK2, no study investigated their role and broad contribution to colorectal cancer." (PMID 35454940, 2022). "Despite the lack of a general rule, we can sketch two trends regarding the activity of DYRK2: in cancer-related it has a general negative impact, whereas in non-cancer-related contexts it has a general positive impact." (PMID 36161154, 2022). "Thus, targeting DYRK2 can significantly affect proteostasis via perturbation of both HSF1 and 26S proteasome activity leading to cancer cell death." (PMID 33376136, 2021). "Besides DYRK2, the other DYRK isoforms, especially the class I's, have a long history in the field of cancer." (PMID 33376136, 2021). "Blocking DYRK2 by curcumin could prevent MYC phosphorylation, which is indispensable for cancer cell growth and consequently inhibit cell transformation." (PMID 33937075, 2021). "In summary, we reveal DYRK2 as a novel negative regulator of NOTCH1 levels and activity, which represents a new control mechanism of the expression and function of this transcription factor with potential implications in cancer." (PMID 31605148, 2020). "Nevertheless, not all works state that DYRK2 negatively regulates invasion and metastatic potential of cancer cells." (PMID 32462403, 2020). "The function of DYRK2 in tumorigenesis is not clear, it may function either as a promoter or inhibitor of cancer, depending on the organ context." (PMID 40190550, 2025). "This dual nature of DYRK2 (both pro- and anti-cancer effects) is not unusual for kinases." (PMID 40190550, 2025).
cancer (continued). "We provide evidence that DYRK2 is involved in FBXW7 stability control in response to DNA damage, with important consequences on cell survival, and rendering cancer cells sensitive to the chemotherapy drug Paclitaxel and anti-cancer BET (Bromodomain and Extra-Terminal motif) inhibitors." (PMID 36934104, 2023). "Hence, the effect of dual inhibition of DYRK2 and HSF1 could indeed be additive and needs to be explored in the context of cancer reduction." (PMID 36622366, 2023). "Thus, DYRK2 inhibition, by impairing both supporting mechanisms, might be an excellent way to tackle not only TNBC cells, but also other aneuploid cancer cells that depend on such support mechanisms, independently on their genetic background." (PMID 33268814, 2021). "Hence, it is also important to decipher the molecular functions of DYRK2 in noncancer models or as a potential cancer driver." (PMID 33376136, 2021).
infection (1 paper, 2015). The state of being infected such as from the introduction of a foreign agent such as serum, vaccine, antigenic substance or organism. "Compared with the control groups, the secreted IFN-β proteins were markedly higher in the DYRK2 knockdown THP-1 cells following infection with SeV and HSV-1." (PMID 26407194, 2015). "However, the interaction between DYRK2 and TBK1 became evident 8 hours after infection, gradually increased between 8 and 12 hours after stimulation, and then completely disappeared." (PMID 26407194, 2015).
nervous system disease (1 paper, 2022). "In the present work, we reviewed current data on DYRK2 function with regards to neuronal morphogenesis, nervous system development, and nervous system disease." (PMID 36161154, 2022). "Below we review the available current literature on DYRK2 with regards (i) neuronal morphogenesis; (ii) nervous system development and (iii) nervous system disease." (PMID 36161154, 2022).
DYRK2 also shares sentences with these, for which no sentence is quoted: colon adenocarcinoma (2 papers); sarcoma (2); Sepsis (2); acute myeloid leukemia (1); breast ductal carcinoma (1); breast invasive carcinoma (1); clear cell renal cell carcinoma (1); COVID-19 (1); diabetes (1); ependymoma (1); esophageal adenocarcinoma (1); gastric adenocarcinoma (1); glioblastoma (1); head and neck squamous cell carcinoma (1); intestinal cancer (1); Kidney (1); Kidney Chromophobe (1); kidney tumors (1); liposarcoma (1); mesothelioma (1); metastatic disease (1); myocardial infarction (1); neurodevelopmental disorder (1); Obesity (1); osteosarcoma (1); ovarian serous cystadenocarcinoma (1); prostate adenocarcinoma (1); rectal cancer (1); renal carcinoma (1); renal cell carcinoma (1).
A further 7 diseases each share a sentence with DYRK2 in 1 paper.